CD4 (CD4 molecule)
Diseases named in the same sentence as CD4 in open-access papers (continued):
Sharing a sentence is not in itself a finding about the gene and the disease.
infection (continued). "Thus, as the pool of CCR5+ CD4 T cells decreases, CD4-expressing mDC and monocyte/macrophages may become increasingly more important as targets for infection, and therefore more susceptible to activation via cytoplasmic RLR." (PMID 24455433, 2013). "The remarkable decrease of CD4+ T cells, including Treg cells, during the acute phase of infection may contribute to the loss of immunological memory and generate helpless but unregulated cytotoxic T cell responses observed in vaccine studies and recurrent human infection." (PMID 22905277, 2012). "Finally, since CD200R expression in mouse depended on chronic Ag exposure, we investigated the association between CD200Rhi CD4 T cells and infection intensity, and thus Ag load, in a cohort (n = 29, 6–16 years) of young individuals which included a number of healthy controls (n = 8)." (PMID 22496920, 2012). "Bystander activation may be important for HIV replication in vivo, as this would be expected to increase the pool of target cells permissive for productive infection and to contribute to activation induced cell death of CD4 and CD8 T cells associated with HIV infection." (PMID 21819585, 2011). "Given that sexual transmission is inefficient, and our determination that α4β7 CD4+ T cells are highly susceptible to productive infection it is reasonable to assume that the ability of a virus to bind to α4β7 may be particularly relevant at an early stage of infection." (PMID 21284901, 2011). "In addition, loss of ICP34.5 also elevates HSV specific CD4+ T cell responses during infection." (PMID 21994775, 2011). "HIV-1 gp120 recognizes CD4 as its main receptor even though it is well known to bind other cell receptors such as the galactocerebroside molecule (GalC) determining a wide array of biological effects from infection of susceptible cells to induction of signal transduction intracellular pathways." (PMID 21612582, 2011). "Intracellular staining for IFNγ revealed that the frequency and absolute number of CD4+ T-cells producing the cytokine upon re-stimulation with C. pneumoniae were higher in TLR2/4 double-deficient when compared to wild type mice especially day 9 post infection." (PMID 22096480, 2011). "In this seminal work, the authors noted that “The relation between the severity of illness and in vitro-replication potential of viruses suggests that during the course of an infection, selection may occur for variants that replicate efficiently in CD4 T cells”." (PMID 21284905, 2011). "Indeed, α4β7 is expressed at high levels on a subset of CD4+ T cells that are particularly susceptible to infection and it has been proposed that the specific affinity of HIV-1 gp120 for α4β7 provides a way for HIV-1 to target susceptible cells at an early stage of transmission." (PMID 21738472, 2011). "Furthermore, the data also suggest that mucosal transmission may support early replication of phenotypically diverse variants, while slowing the rate of CD4+ T cell decline during the initial stages of infection." (PMID 20942954, 2010). "It has been recently found that cell-associated viral loads in CD4+ Tcm are considerably lower in SM than RM, despite equivalent or higher Tem infection levels, which might enable better immune cell homeostasis in infected SM (G.S. and M.P; unpublished observations)." (PMID 20865163, 2010). "However, brain macrophages and microglia are the predominant targets for HIV-1 in the brain, and the presence of highly mac-tropic variants there may simply reflect an adaptation for infection of these low CD4 cell types." (PMID 20507591, 2010). "However, our findings concur because HIV-1 particles captured by iDCs were exocytosed in association with exosomes and could mediate trans-infection of CD4+ T cells." (PMID 20360840, 2010).
infection (continued). "First, they could suppress the early generation of anti-parasitic CD4+ T cells responses that are detrimental to the host, and second, they can modulate pathogenic T cell responses to reduce parasite tissue sequestration later during infection." (PMID 21170302, 2010). "Moreover, a higher level of SIVmneCl8 replication during primary infection of the intrarectally inoculated macaques was associated with lower overall plasma viral load and slower decline in CD4+ T cells, even though SIVmne027 eventually became the dominant virus." (PMID 20942954, 2010). "In CD4-deficient mice, we have the additional potential variable that a CD4-dependent antibody response might also be inhibited during the vaccination phase relative to mice treated with antibody immediately prior to and during the early phases of infection." (PMID 18823549, 2008). "Indeed, infection in rhesus macaques of Indian origin is characterized by profiles of high viral load and rapid decrease of CD4+ T cell counts associated with atypical anti-SIV immune response that may not be relevant to the human situation." (PMID 18347738, 2008). "Upon challenge infection, elevated IgG- and IgA-secreting plasma cells, germinal center B cells, and memory B cells were observed, and CD4+, CD8+ T-cells, as well as both Th1 (IFN-γ) and Th2 (IL-4, IL-5) cytokines, were also increased." (PMID 41599200, 2026). "Conversely, in 17XL infections, CD4+ T cell responses are often suppressed or dysregulated, impairing both antibody‐mediated and cellular defences." (PMID 41461395, 2026). "Specifically, HFD mice had reduced proinflammatory cytokines in the lungs early in infection and increased CD4+ T cells late in infection." (PMID 42059501, 2026). "During the peak of infection, T-cell frequencies across all peptides were similar, but at infection resolution, the frequency of pp65 and gB-specific CD4+IFNγ+ T cells was significantly higher than gL/pUL128L." (PMID 41599037, 2026). "CD4+ T cell activation, B cell‐mediated antibody production, and effective regulation of pro‐inflammatory cytokines all play central roles in containing infection." (PMID 41461395, 2026). "We propose that HIV-1 has evolved to selectively activate CD4 signalling during cell-cell spread to regulate infection at the step of the NPC, offering an explanation for how resting T cells can be infected in vivo." (PMID 42092137, 2026). "Our experiment data determine that subjects with breakthrough infections exhibit significantly enhanced frequencies and polyfunctionality of CD4+ TRM cells, along with elevated germinal centre (GC) B‐cell responses in the NP mucosa." (PMID 41527553, 2026). "Early infection was marked by elevated lung CD4+ T cells (Th17/Treg), diminished Th1 cells and neutrophils, and increased blood cytokines (IFN-γ, IL-21, IL-6, IL-27)." (PMID 42112327, 2026). "For example, Khan and colleagues reported that early infection with the mouse intestinal nematode Heligsomosoides polygyrus can suppress the response of T CD4+ and CD8+ cells, as well as the production of IL‐12 and IFN‐γ during T. gondii infection." (PMID 41399974, 2026). "Recruitment of TLR5‐dependent immune cells via the CCL2/CCR2 pathway is critical to the development of functional CD4+ T‐cell‐mediated immunity, which helps control bacterial colonization and decreases the degree of infection." (PMID 41457476, 2026). "We demonstrate that KLRG1 restricts CD4+ T cells to the lung vasculature early during infection, and limits lesion homing at chronic stages." (PMID 41643900, 2026). "Here, we find that, after IAV infection, antigen-specific CD4 TRM persist in the nasal tissue (NT) compartment after infection and provide protection upon heterosubtypic challenge." (PMID 41941276, 2026). "Both scRNA-seq and flow cytometry confirmed that infection markedly upregulated LAG3 on CD4+ T cells." (PMID 42192546, 2026).
infection (continued). "Using murine models, we found that infection induced a robust expansion of CD4 T-cells expressing granzyme B, perforin, and IFN-γ." (PMID 42206042, 2026). "Although cytotoxic CD4 T-cells (CD4 CTLs) have recently been recognized as crucial effectors in infections and inflammation, the mechanisms that control their differentiation and impact on pathological outcomes remain largely undefined." (PMID 42206042, 2026). "In contrast, DCs remain more functional in 17XNL infections, leading to robust activation of CD4+ T cells and effective adaptive immunity." (PMID 41461395, 2026). "SBTI donors were associated with an increased TH1 IFNGhigh:TH1/TFH ratio among the cytokine producing cells, paralleling previous observations that hybrid immunity (SARS-CoV-2 vaccination and infection) increases frequencies of IFNγ-releasing CD4 T cells." (PMID 41384750, 2026). "Several factors have been associated with their development, including low CD4+ T-cell counts, specific HLA genotype, prolonged infection duration, viral subtype, high viral load, and exposure to HIV-1 multiple infection." (PMID 41481608, 2026). "In non‐lethal 17XNL infections, CD4+ T cells promote B cell maturation and antibody production, while also secreting cytokines that support macrophage activation." (PMID 41461395, 2026). "Flow cytometry showed an early immune response at 8 days post-infection, with increased CD4 T cells, CD8 T cells, B cells, and innate immune cells." (PMID 41511094, 2026). "CD4+ T-cells were then infected with HVS at a multiplicity of infection (MOI) of 0.5 and activated in a flask coated with anti-CD3/anti-CD28 antibodies for three days." (PMID 41596728, 2026). "Studies have shown that CRISPR-Cas9-mediated integration of anti-HIV CARs into the CCR5 locus creates HIV-resistant T cells, preventing the infection of CD4+ CARs and preserving their cytotoxic function." (PMID 41424846, 2026). "These responses were functionally robust, with enhanced antigen specificity and cytokine production of CD4+ T cells in subjects with BR infection." (PMID 41527553, 2026). "Subjects with breakthrough infections exhibited significantly higher frequencies of CD4+ TEM and GC B cells, as well as enhanced SARS‐CoV‐2–specific CD4+ T‐cell responses, including polyfunctionality and cytokine production." (PMID 41527553, 2026). "By 26 days post-infection, the inflammation had largely resolved, but low-level immune infiltration persisted, characterized by CD4 T cells, CD8 T cells, and B cells." (PMID 41511094, 2026). "There are higher proliferation rates and upregulation of surface activation markers in CD4 cells in Giardia infection." (PMID 41970608, 2026). "A decreased CD4+/CD8+ ratio reflects impaired immune competence and elevated infection risk, establishing the clinical relevance of T-lymphocyte subset alterations in COPD." (PMID 40963560, 2025). "Our results indicate that microglia, macrophages, and CD4+ T cells are all producing IFN-γ following infection, and have nearly equal expression of IFN-γ per cell." (PMID 40471948, 2025). "In contrast, ART-treated PLHIV with a CD4+ T-cell count above 500 cells/μL manifest similar infections to those seen in HIV-negative individuals." (PMID 40260259, 2025). "A NOD scid gamma (NSG) mouse was reconstituted with 5 million total memory CD4+ T cells from a human elite controller donor, followed five weeks later by high titer infection with the HIV-1 subtype B strain JR-CSF." (PMID 40654951, 2025). "Compared with ECs, HIV-specific CD8+ T cells in PTCs presented decreased activation levels, lower frequencies, and a reduced ability to inhibit the infection of autologous CD4+ T cells." (PMID 40070826, 2025). "Regarding SARS-CoV-2-specific T cells generated by natural infection and vaccination, there are mostly central memory and effector memory CD4+ T cells and effector memory and terminally differentiated effector CD8+ cells." (PMID 41346576, 2025).
infection (continued). "In vaginal CD4 + T cells, the H. timonensis-induced uptake results in productive infection of CD4 + T cells." (PMID 40874742, 2025). "We found HSV-specific TCR transgenic gDT-II CD4+ T cells aggregating one day after infection by intravital imaging, indicating antigen-specific interactions with antigen-presenting cells that lead to T cell activation." (PMID 39994207, 2025). "Lactic acid also inhibits CD4+ T-cell motility by interfering with glycolysis, which is essential for CD4+ T cells to migrate to sites of infection." (PMID 40422863, 2025). "Utilizing a “two-hit” mouse model, we demonstrated that pharmacological blockade and in vivo knockdown of ARG2 enhanced T cell immune responses against secondary infections by restoring CD4+ T cells, reducing bacterial loads and improving survival rates." (PMID 40860137, 2025). "We analyzed proviral integration sites and relative expression levels of genic integration targets for evidence of differentiation of infected naive T cells into memory CD4+ T cells between the times of infection and sample collection." (PMID 40048262, 2025). "The release of these inflammatory signals attracts more CD4 T cells to the site, perpetuating a cycle of infection and cell death." (PMID 40072080, 2025). "Kidney transplant infections directly caused decreases in CD4 + CD25+/CD4+ T cells, CD8 + CD25+/CD8+ T cells, and HLA‐DR+ monocytes, reflecting differential immune modulation based on infection type." (PMID 41321698, 2025). "Viral production in HIV-infected individuals results from a dynamic process involving continuous rounds of de novo infection and replication in CD4 T cells, along with the rapid turnover of both cell-free virus and virus-producing cells." (PMID 39997464, 2025). "Using a mouse model of concomitant immunity and subsequent aerosol infection, we demonstrate that counter regulation between neutrophils and CD4 T cells occurs very early during infection and governs these distinct pathologies." (PMID 40736456, 2025). "As expected, the T-tropic JRCSF viral strain only showed infection in CD4+ T cells, whereas the M/T-tropic YU2 infected both cell-types." (PMID 40284910, 2025). "Pronounced infection can then be found in the gut lymphoid tissue, which then suffers a rapid depletion of CD4 + T cells, found in both this model and in PWH." (PMID 40386405, 2025). "When the population dynamics of the infection of CD4 T-cells is considered then the force of infection from a deterministic view depends on the mean number of [Vtot] and the total number of infected T-cells." (PMID 41157648, 2025). "In contrast to the frequency of Ki-67-positive CD19+ B cells that remained significantly elevated, the frequency of Ki-67-positive CD4+ T cells rapidly declined after a week, and all CD4+ T cells disappeared approximately two weeks post-infection." (PMID 40733503, 2025). "This suppression is mediated by infection-induced CD4+Foxp3+ regulatory T cells (Tregs), as their depletion reverses the protective effect, leading to aggravated AAI." (PMID 40432048, 2025). "This further highlighted that the longer infection time of acute SIV infection still primarily allowed for the infiltration of CD4 + CTLs compared to other CD4 + T cells." (PMID 40386405, 2025). "In subsequent experiments, CD4+ Tcells were infected with PEDV at a multiplicity of infection (MOI) of 1.0PFU/cell and harvested at the designated times post-infection." (PMID 40094365, 2025). "Following infection, these cells release chemokines like IL-1β and IL-10, which promote the differentiation of naive CD4+ T cells towards the Th17 lineage while suppressing the differentiation and function of Treg cells." (PMID 41425878, 2025). "The results showed that the level of tissue-resident CD4+ T cells after BP-L1 infection was significantly higher than that after vaccine immunization (P < 0.0001), BP-L2 (P < 0.01) and CS (P < 0.001) challenge." (PMID 40568708, 2025).
infection (continued). "Colonic Tregs expressing T-bet accumulated during infection and suppressed the expansion of cytotoxic CD4+ T cells in superspreader hosts, thus ameliorating the intestinal immunopathology." (PMID 40924026, 2025). "We found increased T cell concentration, which included CD4+CCR5+ cells in the presence of TV infection." (PMID 40313463, 2025). "TGF-β has been shown to increase CCR5 expression and to promote infection of both resting and activated memory CD4+ T cells in vitro, suggesting that TGF-β can enhance CCR5-tropic virus spread under certain conditions." (PMID 41573547, 2025). "This abortive infection of CD4+ T cells inducing pyroptosis contributes to chronic inflammation and immune cell depletion." (PMID 40072080, 2025). "Females mount a more robust acute inflammatory response to infection than males, have higher levels of CD4 + lymphocytes and CD4/CD8 ratios, and show greater T cell activation and proliferation, B cell numbers, and immunoglobulin levels." (PMID 40153220, 2025). "All categories were affected by infection, and the pattern was different in lean and obese animals, except in CD4+ Tem cells, where longitudinal changes were similar in both groups." (PMID 40027795, 2025). "More significantly, CECs, through ROS, enhance HIV replication and infection in CD4+ T cells, making them more prone to HIV infection." (PMID 41381803, 2025). "While boost immunization did not have a significant influence on the frequency of S-specific memory T cells In the lungs, XBB.1.5 infection clearly expanded both S-specific CD4 and CD8 memory T cells." (PMID 40562777, 2025). "Based on the literature and our findings, we believe that CD4+ Th1 cells have an important role involved in the clearance of N40 and resolution of Lyme arthritis, even during long-term infection." (PMID 40793757, 2025). "This is in contrast to our results wherein all mice showed productive infection and CD4+ T cell decline with the HIV-1C 93IN101 virus." (PMID 40308596, 2025). "Given the enhanced activity of CD4+ T cells under HT042 treatment in an infection-like environment, we assessed the expression of transcription factors and signature cytokines associated with CD4+ T helper (Th) cell subsets following Con A stimulation." (PMID 40429990, 2025). "The depletion of CD4+ T cells, which play a pivotal role in granuloma formation and TB containment, further impairs the body’s ability to suppress active infection." (PMID 40430808, 2025). "Anti-SARS-CoV-2 N IHC confirmed these findings and the superior defect of CD4 + cell-depleted animals to resolve infection." (PMID 40920821, 2025). "Although HIV-1 is known to enter the brain early in infection via “Trojan horse” leukocytes, including infected monocytes and CD4+T cells, the specific cellular phenotypes facilitating this process during acute infection remain incompletely characterized." (PMID 40386405, 2025). "In contrast, a newly infected CD4+ T lymphocyte can contain hundreds to thousands of US HIV RNA copies on the peak of infection." (PMID 41282897, 2025). "Infection of CD4+ T cells using lentivirus harboring sh-NR4A1 revealed that NR4A1 silencing caused the NR4A1 and BACH2 downregulation in the presence of modeling and daphnetin treatments." (PMID 41462398, 2025). "Siglec-1 can also act to concentrate HIV and transfer it to the CD4/CCR5 entry receptors to facilitate productive infection." (PMID 39861894, 2025). "This strategy induced anti-HBs antibody and CD4 T-cell–dependent control of infection in mice with HBsAg levels at 103 IU/mL or lower." (PMID 40740767, 2025). "Although lectin receptors are predominantly involved in endocytic uptake and associated first-phase transfer, they can also concentrate the virus on the cell surface, leading to infection via CD4 and CCR5/CXCR4." (PMID 40929143, 2025).